HOTAIR (HOX transcript antisense RNA)
Diseases named in the same sentence as HOTAIR in open-access papers (continued):
Sharing a sentence is not in itself a finding about the gene and the disease.
ovarian carcinoma (94 papers, 2015 to 2025). A malignant neoplasm originating from the surface ovarian epithelium. "For instance, a previous study showed that HOTAIR overexpression is linked to platinum resistance in ovarian cancer by sustaining DDR." (PMID 39055884, 2024). "For instance, HOTAIR overexpression appeared to be linked to platinum resistance in ovarian cancer by sustaining DDR and the activation of nuclear factor kappa B (NF-κB)." (PMID 39055884, 2024). "Teschendorff AE, etc. reported that HOTAIR is highly expressed in ovarian cancer and is associated with poor prognosis and carboplatin resistance." (PMID 31391118, 2019). "Lnc-HOTAIR has been shown to negatively regulate this miRNA in lung and ovarian cancers and its overexpression has been associated with a poor prognosis, metastasis promotion and carcinogenesis in several cancers." (PMID 30845775, 2019). "In ovarian cancer, HOTAIR overexpression was associated with poor differentiation, advanced FIGO stage and lymph node metastasis." (PMID 32039022, 2019). "HOTAIR was the most investigated lncRNA and reported by four studies, the pooled HR showed that high HOTAIR expression was significantly associated with shorter OS in ovarian cancer." (PMID 28118613, 2017). "In the DisLncPri predicting result list, we found 4 novel lncRNAs in top 20 (GAS5 at 1, MALAT1 at 4, MEG3 at 6 and HOTAIR at 9) that were recently associated with ovarian cancer." (PMID 27992375, 2017). "High HOTAIR expression was associated with shorter overall survival in ovarian cancer (pooled HR: 2.05, 95% CI: 1.51-2.77, P < 0.001)." (PMID 28118613, 2017). "We analyzed HOTAIR expression and associated surrogate DNA methylation (DNAme) in 134 primary ovarian cancer cases (63 received carboplatin, 55 received cisplatin and 16 no chemotherapy)." (PMID 26497652, 2015). "Moreover, downregulation of HOTAIR suppressed cell proliferation and enhanced paclitaxel sensitivity as well as caused G2/M phase arrest in ovarian cancer cells." (PMID 36105363, 2022). "Similarly, overexpression of HOTAIR is associated with multi-drug resistance in ovarian cancer patients via inducing NF-κB." (PMID 33809601, 2021). "Although recent studies found that overexpression of HOTAIR could lead to chemoresistance in ovarian cancer, the underlying molecular mechanism needs to be further investigated." (PMID 32349783, 2020). "In conclusion, our meta-analysis suggested that LncRNAs could function as potential prognostic markers for ovarian cancer patients and high expression HOTAIR was associated with shorter overall survival in ovarian cancer." (PMID 28118613, 2017). "Interestingly, single nucleotide polymorphisms in HOTAIR were recently found to correlate with susceptibility to ovarian cancer." (PMID 28649178, 2017). "Moreover, in several ovarian cancer cell lines, the expression of HOTAIR causes resistance to cisplatin through wnt/β-catenin pathway activation." (PMID 28637507, 2017). "In this study, we hypothesized that abnormal expression of HOTAIR and common variants of HOTAIR are associated with risk of Epithelial ovarian cancer (EOC)." (PMID 27166268, 2016). "Similarly, evidences demonstrate that overexpression of HOTAIR could cause platinum resistance of ovarian cancer by inducing NF-κB and downstream target gene, interleukin-6 (IL-6)." (PMID 32245498, 2020). "HOTAIR was also expressed at a higher level (log 2-fold change −2.26, FDR p-value < 0.05) in high-TP73 tumours and has been linked to chemoresistance in ovarian cancers." (PMID 40244040, 2025). "The top enriched pathways included Ovarian Cancer Signaling (−log(p) = 3.05), HOTAIR Regulatory Pathways (−log(p) = 3.45), and SUMOylation of transcription factors (−log(p) = 3.13)." (PMID 40050615, 2025). "Interfering HOTAIR in ovarian cancer has the potential to decrease cisplatin‐induced autophagy, offering a novel therapeutic approach for ovarian cancer treatment." (PMID 37961996, 2024).
ovarian carcinoma (continued). "The mechanistic role of HOTAIR has been found to be crucial in developing various ovarian conditions, such as polycystic ovary syndrome, ovarian cancer, and endometriosis." (PMID 38267415, 2024). "For example, lncRNA HOTAIR is aberrantly expressed in ovarian cancer cells, exerting regulatory control over cisplatin‐induced autophagy." (PMID 37961996, 2024). "Second, we studied the inhibitory effects of low expression of lncRNA HOTAIR after shRNA downregulation on the invasion of matrix gel in epithelial ovarian cancer cells and nude mouse tumorigenicity, and further investigated the related molecular mechanisms." (PMID 38070058, 2023). "In our study, down-regulation of the lncRNA HOTAIR in SKOV3 epithelial ovarian cancer cells reduced the expression of zeb1 and TGF-β1." (PMID 38070058, 2023). "In ovarian cancer, inhibiting HOTAIR expression in ovarian cancer cells prevents tumorigenesis and metastasis, and HOTAIR up-regulates c-Myc in breast and ovarian cancers, thereby promoting cancer cell proliferation." (PMID 36924407, 2023). "In brief, in this research, lncRNA HOTAIR downregulation caused a decrease in zeb1 and TGF-β1 but an increase in E-cadherin in epithelial ovarian cancer SKOV3 cells." (PMID 38070058, 2023). "Due to the rapid development in next generation sequencing methods, various lncRNAs, such as ANRIL, CCAT1, FAL1, H19, MALAT1, and HOTAIR, have been discovered in ovarian cancer." (PMID 35326706, 2022). "Aberrant overexpression of HOTAIR contributes to the initiation, growth, and invasiveness of ovarian cancer." (PMID 35624588, 2022). "HOTAIR facilitated paclitaxel resistance by regulation of checkpoint kinase 1 (CHEK1) in ovarian cancer." (PMID 36105363, 2022). "HOTAIR upregulation has been shown to increase the proliferation, migration, and invasiveness of ovarian cancer cells, while the inhibition of HOTAIR represses cell viability and promotes apoptosis." (PMID 35624588, 2022). "HOTAIR has been recently discovered to enhance the invasion and migration of ovarian cancer progression by regulating EZH2, as well as regulating the expression of miR-193a and ODK2, via introducing H3K27me3." (PMID 35326706, 2022). "Consistently, depletion of HOTAIR reduced cisplatin resistance via attenuating cisplatin-mediated autophagy in ovarian cancer." (PMID 36105363, 2022). "HOTAIR has been reported to be a key regulator of cancer, including colorectal, prostate, gastric, and ovarian cancers." (PMID 33809601, 2021). "The involvement of HOTAIR functional SNPs in oncogenesis has been previously reported in a variety of cancer types, including ovarian cancer." (PMID 33667269, 2021). "The upregulation of HOTAIR contributes to the progression of ovarian cancer acting as a ceRNA to regulate the expression of Rab22a through the competitive binding of miR-373." (PMID 33540611, 2021). "In ovarian cancer cells, HOTAIR positively stimulates CCND1 and CCND2 genes, whose upregulation is associated with tumor progression." (PMID 33540611, 2021). "Using HOTAIR as a potential target for treating ovarian cancer has therefore been suggested for possible clinical practice." (PMID 33667269, 2021). "In ovarian cancer, emerging evidence confirms the involvement of HOTAIR in cancer progression and drug-resistance, possibly though promoting mesenchymal stem cell formation." (PMID 33667269, 2021). "Congruently, the inhibition of HOTAIR resulted in high expression of miR-206 and reduced levels of both cyclins indicating a role for the HOTAIR/miR-206/Cyclin B axis in ovarian cancer." (PMID 34204094, 2021). "The overexpression of HOTAIR in epithelial ovarian cancer cells increases cancer invasiveness and metastasis." (PMID 34638965, 2021). "Since endometriosis shares features with cancer, these results make HOTAIR a possible target for future endometriosis or ovarian cancer therapies." (PMID 34638965, 2021).
ovarian carcinoma (continued). "MiR-200c overexpression in ovarian cancer cells and animal models is able to downregulate HOTAIR expression and simultaneously decrease Snail and increase E-cadherin expression, significantly reducing the invasion and tumorigenicity of cancer cells." (PMID 33540611, 2021). "In conclusion, these early studies suggested that the upregulation of HOTAIR contributed to the malignant progression of ovarian cancer." (PMID 34204094, 2021). "In gynecological tumors, HOTAIR is overexpressed in epithelial ovarian cancer tissues and correlates with International Federation of Gynecology and Obstetrics (FIGO) stage, histological grade of the tumor, lymph node metastases, and poor survival." (PMID 32397382, 2020). "Regarding platinum derivatives, HOTAIR is involved in modulating resistance to carboplatin in ovarian cancer." (PMID 32397382, 2020). "Overall, these data suggested that HOTAIR modulates cisplatin chemosensitivity of ovarian cancer cells by miR-138-5p." (PMID 32349783, 2020). "Subsequently, another evidences further validated the correlation of HOTAIR expression with Carboplatin resistance in ovarian cancer." (PMID 32245498, 2020). "It has been shown to be overexpressed in epithelial ovarian cancers, and multivariate analysis has shown that HOTAIR expression is an independent prognostic factor for overall survival (CI 1.04–5.31, p = 0.04)." (PMID 31382546, 2019). "The increased HOTAIR expression induced cisplatin resistance through activatingthe Wnt/b-catenin pathway and promoting cell cycle progression in ovarian cancer." (PMID 31143372, 2019). "Knockdown of HOTAIR in a mouse xenograft model, enhanced the effect of treatment with cisplatin, suggesting its potential as a target to re-sensitize ovarian cancer cells to platinum treatment." (PMID 32039022, 2019). "One study showed increased HOTAIR levels in recurrent platinum resistant ovarian tumours versus primary ovarian cancers and that upregulation of HOTAIR induced platinum resistance by increasing DNA damage response pathways including the NF-κB pathway." (PMID 31382546, 2019). "Expression of HOTAIR was an independent prognostic factor of OS, and its surrogate DNA methylation signature indicated carboplatin resistance in ovarian cancer." (PMID 30446011, 2018). "A recent study also demonstrated that HOTAIR is involved in NF-κB activation and DNA damage response in ovarian cancer cells." (PMID 30353135, 2018). "Overexpression of HOTAIR was recently shown to predict poor patient prognosis and promote tumor metastasis in epithelial ovarian cancer." (PMID 27992375, 2017). "Several dysregulated lncRNAs, such as HOTAIR and LSINCT5, are associated with ovarian cancer survival." (PMID 28154416, 2017). "Our future work will investigate the role of HOTAIR and the lncRNA as a possible therapeutic target in the ovarian cancer stem cell population." (PMID 28420874, 2017). "In ovarian cancer, HOTAIR upregulates the expression of RAB22A by sponging microRNA-373, thereby enhancing tumor proliferation and invasion, and decreasing apoptosis." (PMID 28649178, 2017). "We show ALDH1A1(+) ovarian cancer cells display increased HOTAIR expression and PNA3 treatment decreases ALDH1A1 level in vitro and in vivo." (PMID 28420874, 2017). "To validate these findings we analyzed 175 ovarian cancer samples from Groningen and 49 samples from Bergen and again confirmed that HOTAIR expression is a poor prognostic factor specifically in carboplatin-treated patients." (PMID 26497652, 2015). "Our data demonstrate that HOTAIR and its surrogate DNAme signature play a crucially important role in ovarian cancer biology and provide novel leads to revisit the clinically important field of platinum resistance in this disease." (PMID 26497652, 2015). "The purpose of this study was to investigate the effect of down-regulated HOTAIR expression on tumorgeniesis and metastasis of epithelial ovarian cancer (EOC) CSCs." (PMID 25792974, 2015).
ovarian carcinoma (continued). "In ovarian cancer, it has been shown that the lncRNAs HOTAIR, MALAT1, LINC01127, AB073614, ElncRNA1 and ANRIL modulate the PI3K pathways, while LncRNA HOST2 GAS5, TUBA4B modulate the RAS pathway and lncRNAs TUG1, HOXD-AS1, SNHG20 and EBIC modulate the Wnt/β-catenin pathway." (PMID 39912983, 2025). "However, it is necessary to determine and find direct evidence to demonstrate the function of HOTAIR in carboplatin resistance in ovarian cancer." (PMID 36105363, 2022). "Moreover, HOTAIR is shown to be not only overexpressed in BC but also in ovarian cancer; thus, suggesting that HOTAIR and MALAT1 are oncogenic lncRNAs." (PMID 36387279, 2022). "Overexpression of CHEK1 weakened HOTAIR knockdown-induced paclitaxel sensitivity in ovarian cancer." (PMID 36105363, 2022). "HOTAIR and its DNA methylation file suggest carboplatin resistance in ovarian cancer patients." (PMID 36105363, 2022). "Paclitaxel treatment increased the expression of HOTAIR in ovarian cancer cells." (PMID 36105363, 2022). "In ovarian cancer, NF-κB transcriptionally upregulates HOTAIR expression during cisplatin-induced DNA damage, and HOTAIR facilitates degradation of the NF-κB inhibitor IκBα and thus enhances NF-κB activation, thereby creating a feed-forward regulatory circuit between NF-κB and HOTAIR." (PMID 36471329, 2022). "In addition, other miRNAs (such as miR-34a and miR-454) can be involved in regulating the chemosensitivity of ovarian cancer through the functional interaction with HOTAIR." (PMID 33540611, 2021). "Interestingly, our analysis did not identify lncRNAs that had previously been reported to be associated with ovarian cancer, such as UCA1, HOTAIR, XIST, or H1913." (PMID 33499129, 2021). "HOTAIR, a highly expressed lncRNA in ovarian cancer tissues and cell lines, has been found to be positively correlated with advanced tumor stages, high histological grade, lymph node metastasis, drug resistance, and poor prognosis of ovarian cancer patients." (PMID 34512721, 2021). "Furthermore, the downregulation of HOTAIR is able to reverse cisplatin resistance of ovarian cancer cells by upregulation of miR-138-5p." (PMID 33540611, 2021). "The ectopic upregulation of HOTAIR augmented the cell proliferation and migration abilities of HOTAIR-deficient non-tumorigenic HeyC2 ovarian cancer cells." (PMID 34204094, 2021). "In addition to ovarian cancer, HOTAIR upregulation was also observed in other gynecological cancers such as cervical and endometrial carcinoma, and its expression levels correlated with poor clinical outcomes." (PMID 33667269, 2021). "Three studies documented the roles of HOTAIR in ovarian cancer." (PMID 34204094, 2021). "Before 2015, it was reported that high expression level of HOTAIR could induce platinum resistance in ovarian cancer cells via DNA methylation." (PMID 33302997, 2020). "In the present study, we demonstrated that HOTAIR/miR-138-5p axis could regulate the DDP-resistance of ovarian cancer by potential targets EZH2 and SIRT1, which could shed light on new therapeutic targets for ovarian cancer treatment." (PMID 32349783, 2020). "Recent studies have shown that HOTAIR is highly expressed in prostate cancer, urothelial carcinoma, colorectal cancers, gastrointestinal stromal tumors, hepatocellular carcinoma, pancreatic tumors, ovarian cancer tissues, and primary breast tumors." (PMID 32785167, 2020). "The results suggested that HOTAIR and miR-138-5p might be implicated in the development of DDP resistance of ovarian cancer cells." (PMID 32349783, 2020). "HOTAIR has been demonstrated to significantly influence chemotherapy in ovarian cancer, indicating that HOTAIR could be a candidate prognostic marker in ovarian cancer patients during chemotherapy." (PMID 29921308, 2018). "The role of HOTAIR in ovarian cancer was widely researched in recent years." (PMID 29921308, 2018).
ovarian carcinoma (continued). "Considering its multiple roles, specific targeting and inhibiting HOTAIR could be a potent strategy for ovarian cancer treatment in the future." (PMID 28649178, 2017). "The deregulation of HOTAIR in ovarian cancer has been reported in many studies." (PMID 28649178, 2017). "The “anti-lncRNA” agent decreased ALDH1A1 activity in ALDH(+) ovarian cancer cells, suggesting HOTAIR inhibition with PNA could reduce the ovarian cancer stem cell population." (PMID 28420874, 2017). "It is suggested that NF-κB/HOTAIR crosslinking contributed to chemoresistance in ovarian cancers." (PMID 27713133, 2017). "In addition, some CD117+CD44+ ovarian cancer stem cells overexpress HOTAIR, and silencing HOTAIR with siRNA impaired the migration and invasion of ovarian cancer stem cells." (PMID 28649178, 2017). "Moreover, HOTAIR down-regulation in xenografted mouse models of ovarian cancer leads to the reduction of tumor weight and the number of peritoneal implants, supporting a role for HOTAIR for in vivo cell growth and/or capacity of adhesion to the peritoneum." (PMID 26992233, 2016). "Similarly, HOTAIR expression led to resistance to cisplatin in several ovarian cancer cell lines through activation of the Wnt/β-catenin pathway." (PMID 26992233, 2016). "HOTAIR, a lncRNA in the mammalian HOXC locus, has been fully explored for its genetic variants, expression level and carcinogenesis, development and progression of multiple cancers, except for ovarian cancer." (PMID 27166268, 2016). "HOTAIR plays a pivotal role in epithelial ovarian cancer (EOC) metastasis and could represent a novel prognostic marker and potential therapeutic target in patients with EOC." (PMID 26448935, 2015). "HOTAIR expression was also associated with lower expression of PCGTs, in particular human embryonic fibroblast PCGTs, in the GRONINGEN set, supporting the role of HOTAIR as an epigenetic regulator of MSCs in ovarian cancer." (PMID 26497652, 2015). "Moreover, HOTAIR promoted cisplatin resistance via regulation of DNA damage response and senescence by activation of NF-κB signaling pathway via suppression of IκBα in ovarian cancer cells." (PMID 36105363, 2022). "Similarly, knockdown of HOTAIR can inhibit autophagy via decreasing autophagy related 7 (ATG7) expression, and the inhibition of cisplatin-induced autophagy by silencing HOTAIR has been shown to enhance the chemotherapeutic efficacy of cisplatin in ovarian cancer." (PMID 34512721, 2021). "Many miRNAs (such as miR-34a and miR-454) reported to be involved in regulating the chemosensitivity of ovarian cancer were regulated by HOTAIR, indicating that HOTAIR may also mediate chemoresistance of ovarian cancer cells by other miRNAs and their target genes." (PMID 32349783, 2020). "Furthermore, HOTAIR promotes proliferation of ovarian cancer cells through regulating PIK3R3." (PMID 27367027, 2016). "A prognostic signature with eleven lncRNAs, including NEAT1, HOTAIR, MALAT1, ANRIL, CCAT2, ZFAS1, UCA1 have been shown to predict poor patient survival and outcome in ovarian cancer patients." (PMID 39912983, 2025). "These researchers further observed decreased expression of HOTAIR, bcl-2, and H19, along with overexpression of MEG3, after treating ovarian cancer cells with DNC, indicating that curcumin exerts its anticancer effects via multiple pathways." (PMID 39830662, 2024). "Our research elucidates the expression relationship between lncRNA HOTAIR, TGF-β1, ZEB1, and E-cadherin in epithelial ovarian cancer." (PMID 38070058, 2023). "Among others, lncRNA HOTAIR, H19, MALAT1, and HOST2 can be used as potential therapeutic targets for ovarian cancer and are closely related to tumorigenesis and metastasis in ovarian cancer." (PMID 35706412, 2022). "HOTAIR modulates CCND1 and CCND2 expression through regulating miR-206 expression in ovarian cancer." (PMID 34592939, 2021).